MIR23AHG (miR-23a/27a/24-2 cluster host gene)
Synonyms: LOC284454; Smyca
Gene: Long non-coding RNA gene on chromosome 19 (13,823,880 to 13,842,928, reverse strand). Ensembl gene ENSG00000267519.
Gene Ontology:
Biological process: miRNA-mediated post-transcriptional gene silencing
Cellular component: RISC complex
Diseases named in the same sentence as MIR23AHG in open-access papers:
MIR23AHG is named in the same sentence as 2 diseases in open-access papers, as found by Europe PMC text mining. Sharing a sentence is not in itself a finding about the gene and the disease.
MIR23AHG shares sentences with these, for which no sentence is quoted: kidney cancer (1 paper); tumor (1).